IGFBP5 (insulin like growth factor binding protein 5)
Diseases named in the same sentence as IGFBP5 in open-access papers (continued):
Sharing a sentence is not in itself a finding about the gene and the disease.
melanoma (continued). "To address this issue, we studied IGFBP5 expression in HEMn-LP normal melanocytes and three human melanoma cell lines (A375, A2058, and UACC903) using quantitative real-time PCR (qRT-PCR)." (PMID 26010068, 2015). "In the future, we plan to utilize proteomics techniques to further explore the changes of protein expression profiles and hope to find new factors that contribute to the inhibition of melanoma progression induced by the overexpression of IGFBP5." (PMID 26010068, 2015). "Our previous study revealed that IGFBP5 exhibited a distinctly different expression pattern in melanoma cells with RNA-sequencing (RNA-Seq)." (PMID 26010068, 2015). "In summary, we have identified IGFBP5 as a novel suppressor of the pathogenesis and metastasis of malignant melanoma by expression-manipulating experiments." (PMID 26010068, 2015). "We have demonstrated that IGFBP5 suppresses melanoma cell growth and metastasis through inhibition of the ERK1/2 and P38-MAPK pathways." (PMID 26010068, 2015). "We observed that the expression of HIF1α was inhibited in melanoma cells overexpressing IGFBP5, which is consistent with the inhibition of ERK1/2 and MAPK activities." (PMID 26010068, 2015). "Here, we reported that IGFBP5 acts as an important tumor suppressor in melanoma tumorigenicity and metastasis by a series of experiments including transwell assay, xenograft model, in vivo tumor metastasis experiment, and RNA-Seq." (PMID 26010068, 2015). "In this study, we identify IGFBP5 as a novel inhibiting factor of tumor growth and metastasis in melanoma." (PMID 26010068, 2015). "Our findings provide new insights into the mechanism by which IGFBP5 suppresses the proliferation and invasion of melanoma cells." (PMID 26010068, 2015). "To date, few reports on IGFBP5 in melanoma have been published." (PMID 35958518, 2022). "Interestingly, clinical data shows that IGFBP5 is overexpressed in melanoma compared to normal pigmental nervus." (PMID 36465383, 2022). "Evidence suggests IGFBP5 plays a prominent role in the advancement of epithelial cancers including, but not limited to, ovarian, breast endometrioid, prostate, pancreatic, and gastric cancers as well as melanoma and glioblastoma." (PMID 36465383, 2022). "Moreover, KMT2D positively regulates the enhancer of the tumor suppressor gene IGFBP5 for melanoma suppression and the enhancers of several tumor suppressor genes (e.g., Socs3, Asxl1 and Arid1A) for lymphoma suppression." (PMID 34194626, 2021). "IGFBP5 acts as a tumor suppressor in human melanoma cells, which is interesting given the hypothesis that vitiligo exists on an “immune spectrum” with melanoma." (PMID 33384688, 2020). "DIRC3 therefore appears to act through IGFBP5 to exert its tumour suppressive effect in melanoma." (PMID 31881017, 2019). "IGFBP5 appears to exert a specific inhibitory effect on melanoma growth and metastasis through inhibition of the ERK1/2 and P38-MAPK pathways, therefore it may qualify as a useful therapeutic target against melanoma and other cancers." (PMID 27713912, 2016). "Furthermore, we analyzed the expression of IGFBP5 by hematoxylin-eosin (H&E) and immunohistochemical (IHC) staining in human pigmented nevus samples (n = 7), primary human melanoma samples (n = 7), and human metastatic melanoma samples (n = 8)." (PMID 26010068, 2015). "Despite the increasing number of studies supporting the role of IGFBP5 in tumorigenesis and metastasis in several types of cancers, its function in the progression of cancer is controversial and few studies have provided mechanistic insights for IGFBP5 in human malignant melanoma (MM)." (PMID 26010068, 2015). "Taken together, these results shed light on the mechanism of IGFBP5 as a potential tumor-suppressor in melanoma progression, indicating that IGFBP5 might be a novel therapeutic target for human melanoma." (PMID 26010068, 2015).
melanoma (continued). "A critical question that has been raised is whether the expression of IGFBP5 clinically correlates with the progression of human melanoma." (PMID 26010068, 2015). "Overexpression of IGFBP5 in A375, a typical human melanoma cell line, inhibited cell malignant behaviors significantly, including in vitro proliferation, anchorage-independent growth, migration and invasion, as well as in vivo tumor growth and pulmonary metastasis." (PMID 26010068, 2015). "All these findings were confirmed by IGFBP5 knockdown in human melanoma cell line A2058." (PMID 26010068, 2015). "Because IGFBP5 appears to exert a specific inhibitory effect on melanoma growth and metastasis, it may qualify as a useful therapeutic target against melanoma and, perhaps, other cancers." (PMID 26010068, 2015). "Migration was augmented up to 30 h of assay time for only AP1S2 and IGFBP5 in A375 melanoma cells." (PMID 24039954, 2013). "To test whether IGFBP5 suppressed melanoma growth and metastasis through inhibition of this signaling pathway, we examined the phosphorylation of ERK and p38-MAPK and found that their phosphorylation levels decreased in A375 IGFBP5 OE cells and increased in A2058 IGFBP5 KD cells." (PMID 26010068, 2015). "Thus, it is imperative to determine the roles of IGFBP5 in melanoma." (PMID 26010068, 2015). "However, the relationship between HIF1α and IGFBP5 in human melanoma cells remains to be verified." (PMID 26010068, 2015). "In their study, DIRC3 levels positively correlated with IGFBP5 in melanoma RNA sequencing samples and they discovered that DIRC3 acts in cis to control expression of IGFBP5." (PMID 36043126, 2022). "In melanoma cells, the histone methyltransferase KMT2D, which can methylate Lys-4 in histone 3, has been found to keep proximal and distal IGFBP5-regulating enhancers in an open state, thereby contributing to high IGFBP5 levels." (PMID 36093095, 2022). "A further example of IGFBP-5 potentially mediating tumor suppression by a ncRNA comes from lncRNA DIRC3, low expression of which is a poor prognostic indicator in melanoma patients." (PMID 35597813, 2022). "The insulin-like growth factor binding protein 5 inhibited MAPK1, resulting in compromised growth and migration ability in melanoma cells." (PMID 26928402, 2016). "In our study, we first found that up-regulation of IGFBP5 decreased HIF1α expression and the other IGFBPs family members, IGFBP2, IGFBP4, IGFBP6, and IGFBP7 to some extent in melanoma cells." (PMID 26010068, 2015). "The melanoma CSC markers SOX2, KLF4, and CD271 exhibited reduced expression profiles in the A375 IGFBP5 OE cells compared to empty vector control cells." (PMID 26010068, 2015). "Taken together, these results suggest that IGFBP5 inhibited both the EMT procession and stem cell properties of melanoma cells." (PMID 26010068, 2015). "Silencing of the new targets AP1S2, IGFBP5, and SOX11 resulted in reproducible effects on melanoma cell invasion and migration but strikingly, miR-211 alone did not influence proliferative and invasive growth characteristics significantly." (PMID 24039954, 2013). "In melanoma cells, where DIRC3 is highly expressed, DIRC3 increases IGFBP5 transcription by preventing the TFs SRY-Box transcription factor 10 (Sox10) and melanocyte inducing transcription factor (MITF) from inhibiting IGFBP5 transcription." (PMID 36093095, 2022). "DIRC3 acts in cis and modifies chromatin structure and suppresses SOX10 binding to the promoter of neighboring insulin-like growth factor binding protein 5 (IGFBP5) gene, which activates this tumor suppressor and inhibits anchorage-independent melanoma cell growth." (PMID 34638331, 2021). "One of the latest reports on the subject showed that over-expression of IGFBP5 levels inhibited the epithelial-mesenchymal transition (EMT) and decreased E-cadherin expression and the key stem cell markers NANOG, SOX2, OCT4, KLF4, and CD133 in human melanoma cell line." (PMID 26569312, 2015).
melanoma (continued). "Although we can’t rule out the possibility that DIRC3 also regulates IGFBP5 independently of SOX10, our results are consistent with a model in which DIRC3 acts locally to block SOX10 chromatin binding at melanoma regulatory elements and activate IGFBP5 expression." (PMID 31881017, 2019).
diabetes (22 papers, 2008 to 2024). "Similar to our cohort, lower IGFBP-5 expression was previously observed in COVID-19 patients, and IGFBPs are linked to diabetes and metabolic disorders." (PMID 38760690, 2024). "The Igfbp5 gene encoding IGFBP5 is low expressed during fasting, cachexia, diabetes, and other conditions that cause skeletal muscle atrophy." (PMID 38160938, 2024). "In individuals with diabetes, increased levels of IGFBP-5 have been shown be associated with diabetes-related complications, such as poor wound healing and profibrotic effects in diabetic cardiovascular disease." (PMID 30392760, 2019). "Expression of transcription factors (ANGPTL2, HP, LEP, SAA1, SAA2), genes related to inflammation (SAA1, LEP), diabetes (IGFBP5) and cancer risk (SAA2) were also elevated upon exposure to 5 nM PhIP.." (PMID 27547236, 2016). "Interestingly, increased expression of Igfbp5 and other Igfbps in the muscle has been demonstrated in other than aging scenarios, for example in diabetes also associated with changes in IL‐6 levels." (PMID 26762731, 2016). "The accumulation of insulin growth factor binding proteins 5 (IGFBP5) and advanced glycation end products (AGEs) entailed in atherosclerosis and diabetes onset, respectively, were also disclosed in vitiligo." (PMID 39337683, 2024). "As apoptosis proteins, IGFBP-5 is involved in kidney-related diseases, such as diabetes, focal segment-sclerosing nephritis, and CKD physiological processes." (PMID 38898508, 2024). "Taken together, these findings indicate that diabetic conditions increase IGFBP5 expression, and that this increase is positively related to diabetes mediated ED." (PMID 35866351, 2023). "Upregulation of IGFBP5 expression was observed in diabetes-related complications, including diabetic neuropathy, diabetic heart disease, and diabetic bone disorder." (PMID 35418167, 2022). "IGFBP5 is known to be upregulated in diabetes in many organs and tissues, including the nervous system." (PMID 35513854, 2022). "We also analysed the secretome of human TMSCs and demonstrated that insulin-like growth factor-binding protein 5 (IGFBP5) is critical for the therapeutic effect of TMSCs in a HFD-induced diabetes mouse model." (PMID 31018536, 2019). "In line with this, we also found decreased levels of insulin-like growth factor binding protein 5, which is known to be involved in cell proliferation, differentiation and apoptosis, in diabetes and other metabolic conditions." (PMID 23915542, 2013). "Our data demonstrate that Igfbp5 expression levels in cardiac vascular endothelial cells are consistently elevated throughout the course of diabetes progression, indicating that Igfbp5 is an important target role for the treatment of diabetic injury in both hearts and kidneys." (PMID 39475009, 2024). "The induction of diabetes in PFKFB3-Mut mice was similar to that in IGFBP5−/− mice." (PMID 35418167, 2022). "Up-regulation of IGFBP5 has also been observed in other organs in diabetes." (PMID 26025657, 2015). "In diabetic rats, IGFBP5 mRNA up-regulation has been observed in the kidney, suggesting that elevated IGFBP5 expression levels could contribute to kidney dysfunction during the course of diabetes." (PMID 26025657, 2015). "Igfbp5 was expressed in both GEC and PCEC and was significantly regulated in GEC in diabetes, as shown in human DKD, and enriched in GEC/PCEC in human kidney." (PMID 38673910, 2024). "Lentiviral shRNA‐mediated knockdown of IGFBP5 significantly enhanced the phosphorylations of AKT and ERK but reduced diabetes‐induced increases in p38 phosphorylation and IGFBP5 expression." (PMID 35866351, 2023). "IGFBP-3, IGFBP-4, IGFBP-5, IGFBP-6 are involved in different kidney disease such as diabetes, FSGS and CKD physiological process as apoptosis proteins, IGFBP-7 has been used in clinical practice as a biomarker for early diagnosis and prognosis of AKI." (PMID 35002740, 2021).
diabetes (continued). "Poor diabetes control predicted lower IGF-1 (r2 = 0.21) and greater IGFBP-1 (r2 = 0.39), IGFBP-5 (r2 = 0.38), and bone-specific alkaline phosphatase (BALP; r2 = 0.41, p < 0.05)." (PMID 18665784, 2008). "Diabetes was induced by STZ injections in IGFBP5−/− mice and IGFBP5+/+ controls (+STZ)." (PMID 35418167, 2022). "The heparin domain of IGFBP-5 mediate the migration of the mesangial cells by combining cdc42 in the high glucose environment, and IGFBP-5 increases in the glomerular hypertrophy of early diabetes." (PMID 35002740, 2021). "Further research is needed to understand the influence of diabetes on native PDL-MSCs on the molecular level and whether using growth factors such as IGFs or their binding proteins would enhance periodontal regeneration in diabetics, in particular IGF-1, IGF-2 and IGFBP-5." (PMID 34940355, 2021).
lung carcinoma (18 papers, 2010 to 2024). "Because the lung cancer-resistant Car-R mouse has greater pulmonary expression of Igfbp5 and of Igfbp2 than the cancer-susceptible SWR/J strain, we hypothesized that overexpression of these genes may suppress lung tumorigenesis." (PMID 22973541, 2012). "In lung cancer, IGFBP5 counteracted RASSF1C-induced ERK1/2-dependent stimulation of the stem cell gene Piwi like RNA-mediated gene silencing 1 (PIWIL1) resulting in re-sensitization of tumor cells to the anti-cancer drug betulinic acid." (PMID 36093095, 2022). "Another meta-analysis of 2686 lung cancer patients examined common polymorphisms within the IGF axis, finding that certain patients had a predisposition to lung cancer due to genetic variations in IGF-I, IGF-II, IGF-1R, IGFBP-3, and IGFBP-5." (PMID 35198099, 2022). "Lower serum levels of IGFBP5 are correlated with a positive lymph node status and poor recurrence-free survival in lung cancer." (PMID 33282953, 2020). "We further show, both at RNA and protein levels, that the secreted protein IGFBP5 correlates with NE-lung cancer cells expressing ASCL1." (PMID 31324758, 2019). "A subsequent study indicated that the RASSF1C-dependent promotion of lung cancer cell proliferation is dependent on IGFBP-5 and PIWIL1, implicating the PIWI-piRNA pathway in tumorigenesis." (PMID 26373553, 2015). "Overexpression of the recombinant Igfbp5 and Igfbp2 genes in two lung cancer cell lines significantly inhibited clonogenicity (P < 0.0001)." (PMID 22973541, 2012). "In humans, overexpression of IGFBP5 inhibited in vitro cell proliferation or angiogenesis in different tumor types, whereas low serum IGFBP5 levels correlated with poor prognosis of lung cancer patients." (PMID 22973541, 2012). "We therefore tested the effects of Igfbp5 and Igfbp2 overexpression on clonogenicity of lung cancer lines." (PMID 22973541, 2012). "Interestingly, lung cancer cells with mutations of resistant genes, such as ABCB5, IGFBP5, MAP4, showed high proliferation treatment by drug AZD7762." (PMID 36180906, 2022). "Also, in a panel of 93 cell lines, established from breast, colon and lung cancers, lower IGFBP5 levels were indicative for a strong response to the IGF1R-specific human monoclonal antibody figitumumab." (PMID 36093095, 2022). "Thus, we wanted to investigate the effect of RASSF1C/ IGFBP-5 interaction on PIWIL1 gene expression in lung cancer cells." (PMID 25007054, 2014). "Therefore, we wanted to study the effect of RASSF1C/IGFBP-5 interaction on PIWIL1 gene expression in lung cancer cells." (PMID 25007054, 2014). "We also show that IGFBP-5 may be an important molecule for modulating RASSF1C/PIWIL1 effects in lung cancer." (PMID 25007054, 2014). "Overexpression of either Igfbp5 or Igfbp2 in two lung cancer cell lines inhibited clonogenicity, suggesting that their upregulation in vivo may protect from tumor predisposition." (PMID 22973541, 2012). "Analogously, genes involved in wound healing and cell migration (i.e., SERPINE1, HMGCR, IGFBP5, and S100A14) or reported as prognostic factors in breast, ovarian, gastric, and lung cancers (i.e., MAPRE1, HSPA1B, and PPME1) were negatively modulated." (PMID 31752957, 2019). "Collectively, these data validated the physiological relevance of IGFBP5 and B4GALT1 as specific secreted protein markers for ASCL1High NE-lung cancers." (PMID 31324758, 2019). "Previously, we have shown that RASSF1C is a binding partner of insulin-like growth factor binding protein 5 (IGFBP-5), which is a member of the IGF binding protein family that has been shown to be critically important in lung cancer progression." (PMID 22591718, 2012). "Among them, IGFBP2, IGFBP3, IGFBP4, IGFBP6 and IGFBP7 showed higher expression levels, especially in gastric, liver and lung cancer cell lines; conversely, IGFBP1, IGFBP5 and IGFBPL1 showed relatively lower expression, particularly in colorectal, gastric and kidney cancer cell lines." (PMID 37088808, 2023).
lung carcinoma (continued). "The IGFBP-5, RASSF1C, and PIWIL1 genes may constitute a new axis in controlling lung cancer cell development and progression." (PMID 25007054, 2014). "Thus, RASSF1C, IGFBP-5, PIWIL1, and the Wnt pathway could function together as a new axis that impacts lung cancer cell growth and progression." (PMID 25007054, 2014). "Furthermore, we found that lung cancer cells co-expressing RASSF1C and IGFBP-5, but not cells co-expressing RASSF1A and RASSF1C, were as sensitized to BA inhibition as the control cells." (PMID 25007054, 2014). "Interestingly, we found that co-expression of RASSF1C and IGFBP-5 reduced PIWIL1 mRNA and protein levels in lung cancer cell lines, while co-expression of RASSF1A-RASSF1C did not have a major effect on PIWIL1 mRNA levels compared to cells over-expressing RASSF1C." (PMID 25007054, 2014).
glioblastoma (15 papers, 2009 to 2025). The most malignant astrocytic tumor (WHO grade IV). "For instance, in glioblastoma, IGFBP5 can promote tumor invasion through the ROR1/HER2-CREB signaling pathway." (PMID 41282023, 2025). "Studies have found that IGFBP5 can increase the invasion of glioblastoma pleomorphic cells and inhibit cell proliferation through the EMT and Akt signaling pathways." (PMID 37078747, 2023). "To further validate the contribution of these pathways to 12ADT-mediated cytotoxicity, we designed CRISPR guides against three target genes (ERN1, IGFBP3, IGFBP5) and transfected them separately into U251 glioblastoma cells." (PMID 32433555, 2020). "Interestingly, IGFBP5 exhibits a dual role in glioblastoma: on the one hand, it promotes tumor cell invasion by promoting epithelial–mesenchymal transition (EMT); on the other hand, it inhibits tumor cell proliferation by inhibiting the Akt signaling pathway." (PMID 41275376, 2025). "Moreover, in glioblastoma, the binding of insulin-like growth factor-binding protein 5 (IGFBP5) to ROR1 facilitates the formation of a ROR1/HER2 heterodimer, which subsequently induces the expression of genes like ETV5 and FBXW9 to promote glioblastoma stem-like cell invasion and tumorigenesis." (PMID 40869147, 2025).